KRTAP6-1 (keratin associated protein 6-1)
Description:
In the hair cortex, hair keratin intermediate filaments are embedded in an interfilamentous matrix, consisting of hair keratin-associated proteins (KRTAP), which are essential for the formation of a rigid and resistant hair shaft through their extensive disulfide bond cross-linking with abundant cysteine residues of hair keratins. The matrix proteins include the high-sulfur and high-glycine-tyrosine keratins.
Synonyms: C21orf103; KAP6.1
Tractability: No criterion of Open Targets' tractability assessment is met for any kind of drug.
Gene: Protein-coding gene on chromosome 21 (30,613,431 to 30,613,930, reverse strand). Ensembl gene ENSG00000184724.
Pathways (Reactome):
Developmental Biology: Keratinization
Gene Ontology:
Molecular function: protein binding
Biological process: keratinization
Cellular component: cytosol
Genetic constraint (gnomAD): Loss-of-function variants: 7 observed, 6 expected, observed/expected ratio (o/e) 1.17, 90% interval 0.65 to 1.86. That is too few expected variants to judge how well the gene tolerates losing a copy. Missense variants: 78 observed, 92.33 expected, observed/expected ratio (o/e) 0.84, 90% interval 0.7 to 1.02. Synonymous variants: 38 observed, 40.99 expected, observed/expected ratio (o/e) 0.93, 90% interval 0.71 to 1.22.
Homologues: Orthologues: chimpanzee KRTAP6-1 (99% identical).